XBP1 (X-box binding protein 1)
Diseases named in the same sentence as XBP1 in open-access papers (continued):
Sharing a sentence is not in itself a finding about the gene and the disease.
oral squamous cell carcinoma (3 papers, 2019 to 2021). "Similarly, XBP1 deficiency in oral squamous cell carcinoma cells impairs cell invasion and leads to a decrease in the expression of invasion-associated genes including MMP1, MMP3 and PLAUR." (PMID 31064137, 2019). "In addition, elevated levels of XBP1 at primary tumors are statistically associated to the presence of distant metastasis in patients with esophageal carcinoma, hepatocellular carcinoma and oral squamous cell carcinoma." (PMID 31064137, 2019).
osteoarthritis (3 papers, 2018 to 2026). A noninflammatory degenerative joint disease occurring chiefly in older persons, characterized by degeneration of the articular cartilage, hypertrophy of bone at the margins and changes in the synovial membrane. "The temporal analysis of gene expression patterns in GSE89408 RNA-seq validation dataset was conducted for the gene expression levels of PDK1, XBP1 and ACACB across different disease stages, including normal, arthralgia, osteoarthritis, undifferentiated arthritis, RA (early), and RA (established)." (PMID 41583523, 2026).
ovarian tumor (3 papers, 2016 to 2020). "XBP1 has been shown to regulate cDC infiltrating ovarian tumors; accumulation of lipids in the tumor-infiltrating cDC following ER stress and XBP1 activation reduces their ability to present antigens, and thus impairs anti-tumor T-cell responses." (PMID 28580131, 2017). "Indeed, similar findings were described as a result of the ER stress response factor XBP1 activation in ovarian tumor-infiltrated cDCs47." (PMID 33257753, 2020).
preeclampsia (3 papers, 2013 to 2024). Preeclampsia is a hypertensive disorder of pregnancy that is characterized by new-onset hypertension with proteinuria presenting after 20 weeks of gestation, and depending on mild or severe forms may initially present with severe headache, visual disturbances, and hyperreflexia. "Compared to placentas from normotensive pregnancies, placentas from preeclamptic pregnancies (particularly early-onset preeclampsia) exhibit increased IRE1 phosphorylation, XBP1 splicing, and ER luminal dilation." (PMID 39758342, 2024). "Activation of placental UPR pathways including P-IRE1α, ATF6, XBP-1, GRP78 and GRP94 were all reported to be higher in early-onset (< 34 weeks) preeclampsia than in both late-onset preeclampsia and normotensive controls." (PMID 28397763, 2017). "Interestingly, reduced placental growth factor in preeclampsia is associated with nuclear localization of ATF4 and ATF6β (but not ATF6⍺ or XBP1) in the STB layer." (PMID 39758342, 2024). "Likewise, expression of XBP1 is increased in decidual tissues from preeclampsia with and without FGR." (PMID 39758342, 2024).
pulmonary hypertension (3 papers, 2016 to 2024). Increased pressure within the pulmonary circulation due to lung or heart disorder. "On the other hand, it was found that the single nucleotide polymorphism rs619586A>G in MALAT1 is associated with the risk of pulmonary arterial hypertension, increasing the expression of X-box binding protein 1 (XBP1), which inhibits the proliferation of vascular endothelial cells." (PMID 38674413, 2024). "For example, if we want to target XBP1 splicing in SMCs to suppress airway SMC proliferation under pulmonary hypertension, it may affect the EC-SMC interaction and EC proliferation as well." (PMID 27338006, 2016).
renal cell carcinoma (3 papers, 2020 to 2025). "However, the role of XBP1 in the progression of FH mutated renal cell carcinoma has been unrecognized." (PMID 32774853, 2020). "Novel findings from RCC preclinical models reveal that MANF protein drives sunitinib resistance via IRE1α-XBP1 pathway inhibition, while NPTX2 aberrantly activates PI3K-Akt survival signaling in clear cell renal cell carcinoma (ccRCC)." (PMID 41142779, 2025).
renal fibrosis (3 papers, 2021 to 2022). A final common manifestation of a wide variety of chronic kidney diseases characterized by glomerulosclerosis and tubulointerstitial fibrosis. "Hence, our data support the concept that loss of XBP1 aggravates renal fibrosis." (PMID 35765067, 2022). "Our findings uncover the role of ER stress master regulator XBP1, which connect cell cycle regulation to the development of renal fibrosis." (PMID 35765067, 2022). "Different from their approach, we used proximal tubular specific XBP1 conditional knockout mice to highlight the pathogenetic roles of XBP1 downregulation in renal epithelial, aggravating post-injured renal fibrosis." (PMID 35765067, 2022). "In order to explore the potential therapeutic role of adaptive UPR in renal fibrosis, we further study the critical molecule XBP1 in the AKI to CKD transition." (PMID 35765067, 2022). "Our previous work demonstrated that overwhelming ER stress was significantly activated in the unilateral ureteral obstruction (UUO)-induced renal fibrosis and coincident with attenuation of XBP1 expression, adaptive UPR effector." (PMID 35765067, 2022). "As mentioned, ER stress can influence fibrosis, and spliced XBP1 is increased in the thick ascending limb of the nephron in a genetic mouse model of inherited renal fibrosis." (PMID 34625532, 2021). "In addition, we found that UPR initiators PERK, IRE1α, and ATF6 were activated following AKI, while the expression of XBP1 gradually lowered throughout experiments and inversely correlated with the degree of renal fibrosis." (PMID 35765067, 2022). "XBP1 expressions were attenuated after AKI and inversely correlated with the severity of post-AKI renal fibrosis." (PMID 35765067, 2022). "In this mini-review, we discuss the role of UPRs in renal diseases and renal fibrosis, highlight the therapeutic potentials of the modulation of UPRs and the proteostasis of ER, and, in particular, emphasize the role of inositol-requiring protein 1-X-box-binding protein 1 (IRE1-XBP1) signaling." (PMID 34445377, 2021).
Salmonella Infections (3 papers, 2021 to 2025). Infections with bacteria of the genus SALMONELLA. "However, we did not observe any increase in XBP1 recruitment inside the nucleus upon infection at any time point post-infection, suggesting that Salmonella infection upregulates UPR by PERK and ATF6 pathways in HeLa cells." (PMID 40272166, 2025).
tauopathy (3 papers, 2010 to 2024). Neurodegenerative disorders involving deposition of abnormal tau protein isoforms (tau proteins) in neurons and glial cells in the brain. "Our results show both atf-6 and xbp-1 loss of function enhance tauopathy-induced behavior defects in C. elegans, with xbp-1 loss of function additionally increasing tau protein levels and neurodegeneration." (PMID 31570707, 2019). "Taken together, xbp-1 loss of function exacerbates tau-mediated behavioral deficits, increases accumulation of tau protein, and drives tau-dependent neurodegeneration in C. elegans models of tauopathy." (PMID 31570707, 2019). "However, both ATF6 and PERK branches of the UPRER participate in amelioration of tauopathy by constitutively active XBP-1, possibly through endoplasmic reticulum-associated protein degradation (ERAD)." (PMID 31570707, 2019). "Given xbp-1 loss of function enhances tauopathy phenotypes, we hypothesized xbp-1 gain of function might suppress tauopathy." (PMID 31570707, 2019). "These genes include Xbp1, Hspa5, Dnajc3, and members of the Pdi family, which overlap with C. elegans homologs in our transcriptomic dataset and are required for xbp-1s-mediated suppression of tauopathy." (PMID 39060347, 2024). "Furthermore, constitutive activation of master transcription factor XBP-1 ameliorates tauopathy phenotypes." (PMID 31570707, 2019). "Our genetic data suggests that activation of the UPR may play a neuroprotective role in tauopathies because reducing Xbp1 levels exacerbates cellular toxicity." (PMID 20927324, 2010). "Given the known importance of the XBP-1 and ATF-6 branches in UPRER transcriptional regulation, a plausible mechanism of tauopathy suppression involves regulation of specific target gene(s) coordinately upregulated by ATF-6n and XBP-1s transcription factors." (PMID 31570707, 2019). "This demonstrates an absolute requirement for ATF-6 in mediating tauopathy suppression by transgenic constitutively active XBP-1s expression in C. elegans and a previously unappreciated critical crosstalk between ATF-6 and XBP-1 branches of the UPRER in tau proteostasis." (PMID 31570707, 2019).
thymoma (3 papers, 2022). A neoplasm arising from the epithelial cells of the thymus.
vasculitis (3 papers, 2016 to 2022). "XBP1 expression is increased in the areas of blood vessels that have been damaged and inflamed, including atherosclerotic, vasculitis-affected or stent-implanted vessels." (PMID 36426231, 2022). "Based on publicly available human patient transcriptomics data sets, bulk RNA-Seq, and scRNA-Seq from murine KD vasculitis, we show that KD development is associated with increased expression of ER stress signature genes, including IRE1/XBP1 target genes." (PMID 35167493, 2022). "Among the signaling pathways induced in endothelial cells during vasculitis, NF-κB and endoplasmic reticulum stress response protein X-box binding protein-1 (XBP-1) appear important." (PMID 28018358, 2016). "In a local Shwartzman reaction model of TNF-induced vasculitis, XBP-1 contributes to the vascular damage as shown in mice with an endothelium-specific XBP-1 deletion." (PMID 28018358, 2016).
allergic disease (2 papers, 2018 to 2026). An immune response that occurs following re-exposure to an innocuous antigen, and that requires the presence of existing antibodies against that antigen. "Two prominent cytokines, IL5 and IL13, which promote allergies and eosinophilia, are under the control of IRE1a-XBP1 pathway in Th2 lymphocytes." (PMID 30355343, 2018). "Therefore, the IRE1α-XBP1 axis plays a significant role in IgE-dependent and MC-mediated allergic responses and is considered to be a therapeutic target of allergic diseases." (PMID 42196510, 2026).
astrocytoma (2 papers, 2012 to 2021). "Interestingly, despite the low level of XBP1 protein induction in astrocytoma SNB19 cells after infection with TBEV HB171 and LGTV, XBP1 mRNA splicing seemed to occur at a similar level compared to TBEV Neudoerfl infected cells, though with slower kinetics for LGTV." (PMID 34834970, 2021). "Activation of IRE1α resulted in an increase in the expression of the XBP1 transcription factor, and 2OHOA and palmitate (150 μM; 24 h and 48 h) markedly up-regulated IRE1α protein levels in 1321N1, SF-767 and U118 cells and modestly up-regulated mRNA levels in 1321N1 astrocytoma cells." (PMID 23133576, 2012). "The IRE1 activation marker XBP1 was strongly induced in neuronal SH-SY5Y and intestinal Caco-2 cells upon infection with all three TBFV and in astrocytoma SNB19 cells upon infection with TBEV Neudoerfl." (PMID 34834970, 2021). "In contrast, in astrocytoma SNB19 cells, viral replication was reduced significantly with the most pronounced effects observed for GSK2850163, despite the detection of residual XBP1 at later time points." (PMID 34834970, 2021).
autosomal dominant retinitis pigmentosa (2 papers, 2012 to 2014). Autosomal dominant retinitis pigmentosa (RP) is an autosomally dominant inherited retinal dystrophy leading to progressive loss of the photoreceptors and retinal pigment epithelium and resulting in blindness usually after several decades. "With a Drosophila model for autosomal dominant retinitis pigmentosa, Ryoo and colleagues examined the role of XBP1 in photoreceptor cells." (PMID 25530974, 2014). "A recent study from Ryoo and colleagues demonstrates that depletion of XBP1 in Drosophila augments photoreceptor degeneration in ninaE (G69D)−/+, a Drosophila model for autosomal dominant retinitis pigmentosa (ADRP), suggesting that XBP1 is essential for photoreceptor survival during ER stress." (PMID 22715395, 2012).
Cachexia (2 papers, 2025). Severe weight loss, wasting of muscle, loss of appetite, and general debility related to a chronic disease. "Since oxidative stress is an important stimulus for the activation of proteolytic systems and muscle wasting, it is possible that overstimulation of the IRE1α/XBP1 axis also causes muscle wasting through augmenting fatty acid oxidation and oxidative stress during cancer cachexia." (PMID 41249735, 2025).
cardiac ischemia (2 papers, 2021 to 2022). "Collectively, our data demonstrated that electroacupuncture treatment activated XBP1/GRP78/Akt signaling to protect hearts from myocardial ischemia/reperfusion injury." (PMID 34195232, 2021).
chondrodysplasia (2 papers, 2021 to 2026). "In addition, the deletion of XBP1 signaling was found to cause chondrodysplasia and delayed ossification." (PMID 34737845, 2021). "The expression of circTspan3 is significantly downregulated in X-box binding protein 1 (Xbp1) conditional knockout (cKO) mice displaying chondrodysplasia and positively correlates with anabolic markers of cartilage." (PMID 41486887, 2026).
chronic pancreatitis (2 papers, 2021 to 2025). A chronic inflammatory process causing damage and fibrosis of the pancreatic parenchyma. "Interestingly, a recent study indicated that the overaccumulation of PRSS was accompanied by upregulated XBP1 in a mouse model of chronic pancreatitis." (PMID 34621695, 2021).
Co-infection (2 papers, 2025). "Co-infection with productive HIV-1 tended to augment the Mtb-induced decrease in XBP1 expression in astrocytes." (PMID 40420159, 2025).
cystic fibrosis (2 papers, 2017 to 2020). Autosomal recessive disorder caused by pathogenic variants in the CFTR gene (cystic fibrosis transmembrane conductance regulator), which encodes a chloride and bicarbonate channel expressed in epithelial cells, and follow the diagnosis criteria. "Our findings are consistent with a recent report showing that in cystic fibrosis, lung macrophages undergo polarization imbalance, with suppression of M2 polarization associated with activation of the IRE1α/XBP1 axis." (PMID 32520957, 2020).
endometrial tumor (2 papers, 2020 to 2021). "Multiplex immunofluorescence confirmed that PRSS33, CPB2 and XBP1 proteins were significantly highly expressed in the endometrial tumor tissues of patients with elevated DD and FDPs, suggesting that Prevotella could partially promote DD and FDPs by influencing host gene expression." (PMID 34621695, 2021).
endotoxemia (2 papers, 2020 to 2023). "Blockade of miR-674-5p promoted XBP-1 activity, attenuated intestinal inflammation, and expedited intestinal regeneration, resulting in protection against endotoxemia-induced intestinal injury in mice." (PMID 32550011, 2020). "Here, we identified the microRNA (miR)-674-5p/X-box binding protein 1 (XBP-1) axis as a critical regulator and therapeutic target in preventing intestinal crypt cell proliferation during endotoxemia." (PMID 32550011, 2020). "Mechanistically, FT@XBP1 increased the expression of ZO-1 in the intestine and had the potential to restore intestinal barrier integrity and improve antimicrobial defense to alleviate enterogenic endotoxemia and activation of inflammatory signaling pathways." (PMID 38516345, 2023). "Collectively, these data indicate that control of a novel miR-674-5p/XBP-1 signaling axis may mitigate endotoxemia -induced intestinal injury." (PMID 32550011, 2020). "Moreover, we identified the targeting of XBP-1 by miR-674-5p as a potential therapeutic target for improving endotoxemia-induced intestinal injury." (PMID 32550011, 2020). "Elaboration of the HIF-1α/miR-674-5p/XBP-1 signaling pathway not only provides novel and important insight into the pathogenesis of intestinal injury by endotoxemia or endotoxemia, but also suggests a novel miRNA-based therapeutic target for prevention and treatment." (PMID 32550011, 2020). "In this study, we demonstrated that blocking XBP-1 decreased the proliferation of IECs during endotoxemia and that by restraining miR-674-5p expression, enhanced XBP-1 could accelerate IEC proliferation, especially in the crypts, in endotoxemia-induced intestinal injury." (PMID 32550011, 2020). "Moreover, we identified miR-674-5p as a key miRNA that was markedly induced in endotoxemia-induced intestinal injury and was found to target X-box binding protein 1 (XBP-1), which in turn, inhibited intestinal crypt cell proliferation and exacerbated intestinal injury during endotoxemia." (PMID 32550011, 2020). "Since XBP-1 has previously been shown to facilitate cell survival and increase epithelial neoplasia in several pathological conditions, we investigated the role of XBP-1 in endotoxemia-induced IEC injury." (PMID 32550011, 2020).
fibrosarcoma (2 papers, 2015 to 2023). A malignant mesenchymal fibroblastic neoplasm affecting the soft tissue and bone. "Loss of XBP1 has been reported to increase the sensitivity to hypoxia-mediated death of transformed cells and markedly suppress tumour growth in mouse embryonic fibroblasts and human fibrosarcoma cells." (PMID 36997866, 2023).
gallbladder cancer (2 papers, 2020 to 2022). "However, the roles of XBP1 and NAT1 in gallbladder cancer (GBC) are never reported." (PMID 32793479, 2020).
gastric adenocarcinoma (2 papers, 2016 to 2023). "The low SYK expression (p = 2.895 × 10−3), NDRG1_pT346 (p = 3.872 × 10−2), P90RSK (p = 1.991 × 10−3), and TIGAR (p = 2.885 × 10−4) and the high XBP1 expression (p = 8.621 × 10−4) were significantly positively associated with the poor overall survival of STAD (stomach adenocarcinoma) patients." (PMID 36979962, 2023).
glomerular disease (2 papers, 2015 to 2024). "Furthermore, it has been demonstrated that the intact IRE1α-XBP1 pathway plays a cytoprotective role in glomerular diseases associated with podocyte injury." (PMID 38607075, 2024).
Hodgkins lymphoma (2 papers, 2020 to 2022). A heterogeneous group of malignant lymphoid neoplasms of B-cell origin characterized histologically by the presence of Hodgkin and Reed-Sternberg (HRS) cells in the vast majority of cases. "In Hodgkin lymphoma (HL), a chromosomal rearrangement far upstream region of ZHX2 gene results in the transcriptional silence of ZHX2, and two transcription factors, homeodomain protein MSX1 and bZIP protein XBP1, are identified to directly regulate ZHX2 expression." (PMID 36465389, 2022).
hyperandrogenism (2 papers, 2021 to 2022). Excessive secretion of androgens from the adrenal glands or gonads. "In our study, hyperandrogenism induced ER stress and IRE1α-XBP1 pathway activation in ovarian GCs of PCOS model rats." (PMID 36062194, 2022). "In summary, curcumin and aerobic exercise (irisin) can alleviate hyperandrogenism-induced ER stress and suppress the IRE1α-XBP1 pathway, which prevented ovarian GC apoptosis in PCOS-like rats, leading to the improvement in the ovarian microenvironment and promotion of follicular development." (PMID 34987702, 2021).
Hyperinsulinemia (2 papers, 2020 to 2026). An increased concentration of insulin in the blood. "We found that the AlbCre;Xbp1flx/flx mice displayed significantly impaired fasting glycemia, hyperinsulinemia, and impaired glucose tolerance by 50–60 weeks of age, suggesting that hepatic loss of Xbp1 led to a state of metabolic dysregulation similar to that observed in human NAFLD." (PMID 33277471, 2020).